ALK (ALK receptor tyrosine kinase)
Diseases named in the same sentence as ALK in open-access papers (continued):
Sharing a sentence is not in itself a finding about the gene and the disease.
neuroblastoma (continued). "In summary, our results show that CGM097 significantly enhances the antitumor activity of ceritinib in neuroblastoma with aberrantly activated ALK by inducing a complementary set of anti-proliferative and pro-apoptotic signaling." (PMID 28425916, 2017). "Constitutively, activated ALK synergizes with MYCN overexpression in inducing neuroblastoma in animal models, and the co-occurrence of ALK F1174 mutations and MYCN amplification defines a subset of neuroblastoma patients with particularly poor outcome." (PMID 28425916, 2017). "Both N-myc and c-myc have been demonstrated to be capable of inducing the proximal promoter activity of the ALK gene through direct interaction with the E-boxes in neuroblastoma cells." (PMID 28837676, 2017). "Crizotinib was less successful against ALK F1174L neuroblastomas in clinical trial, but showed efficacy in the treatment for ALK R1275Q neuroblastomas." (PMID 28432815, 2017). "We first examined the anti-proliferative and cytotoxic effect of four ALK inhibitors – crizotinib, ceritinib, alectinib and PF06463922 – in four neuroblastoma cell lines that harbor ALK aberrations." (PMID 28425916, 2017). "We used two neuroblastoma cell lines to compare crizotinib and ceritinib treatment in a dose‐dependent and time‐dependent manner using the total ALK, pY ALK, pY1278, pY1604, and pY1586 ALK immunoassays." (PMID 28432815, 2017). "As an initial step towards copy number detection in acelluar biosamples such as blood plasma, we analyzed MYCN and ALK amplification status from cfDNA in medium conditioned by neuroblastoma, medulloblastoma and colon adenocarcinoma cell lines." (PMID 29156716, 2017). "Both N-myc and c-myc can induce the proximal promoter activity of the ALK gene through direct interaction with the E-boxes in neuroblastoma cells." (PMID 28193280, 2017). "recently, deregulated expression of full-length ALK has also been observed in some primary solid tumors derived from various tissues, including GBMs and neuroblastomas." (PMID 28837676, 2017). "Neuroblastoma is a tumor of the peripheral sympathetic nervous system for which only a few driver alterations have been described including MYCN amplification and ALK mutations." (PMID 28423360, 2017). "We next evaluated ddPCR-based MYCN and ALK copy number assessment in blood plasma samples retrospectively collected at diagnosis from 10 neuroblastoma patients with known MYCN status." (PMID 29156716, 2017). "FAM150A and FAM150B are widely expressed, though FAM150B mRNA is most highly expressed in the adrenal gland, pointing to its potential role in the pathogenesis of ALK-positive neuroblastoma." (PMID 28895885, 2017). "MYCN and ALK copy numbers of subcutaneous neuroblastoma xenograft tumors were accurately determined from cell-free DNA in the mouse blood plasma." (PMID 29156716, 2017). "We established droplet digital PCR (ddPCR) protocols for MYCN and ALK copy number status in plasma from neuroblastoma patients." (PMID 29156716, 2017). "We provide exact ALK copy numbers for our neuroblastoma cell line panel and our protocol confirmed the amplified, gain or diploid status in most cell lines." (PMID 29156716, 2017). "We provide exact ALK copy number data for our neuroblastoma cell line panel that adds to previous reports classifying them only as diploid or amplified, and confirmed the reported ALK status with 6 exceptions." (PMID 29156716, 2017). "We also find that neuroblastoma cell lines with ALK aberrations develop resistance to ALK inhibition as a result of MYCN upregulation." (PMID 28425916, 2017). "We describe immunoassays designed to quantitate phosphorylation of ALK, and their use in preclinical models of neuroblastoma, a pediatric malignancy in which gain‐of‐function ALK mutations predict a poor overall outcome to conventional treatment." (PMID 28432815, 2017).
neuroblastoma (continued). "Crizotinib and ceritinib are both under clinical evaluation for the treatment of ALK‐positive neuroblastomas with genetic ALK alterations, and our immunoassays allow for a direct pharmacodynamic preclinical comparison of the two compounds." (PMID 28432815, 2017). "ALK has been identified as a novel therapeutic target in neuroblastoma (NB), but resistance to ALK inhibitors (such as crizotinib) is well recognized." (PMID 29203817, 2017). "Several germline and sporadic mutations predisposing to neuroblastoma development have been identified, including PHOX2B, anaplastic lymphoma kinase (ALK), polypeptide N-acetylgalactosaminyltransferase 14 (GALNT14), and MYCN." (PMID 28358317, 2017). "We further validated copy number detection by ddPCR of cfDNA using our assay for ALK copy number in our neuroblastoma cell line panel." (PMID 29156716, 2017). "As well as MYCN amplification, activating point mutations of ALK and NRAS are associated with high-risk and relapsing neuroblastoma." (PMID 28602975, 2017). "ATRA has been previously shown to down-regulate ALK in neuroblastoma cell lines and induce apoptosis selectively in those harboring activated ALK (NB-39-nu and SH-SY5Y)." (PMID 29018329, 2017). "In this study, we have globally analyzed the effect of Crizotinib treatment on phosphoproteome changes in three representative neuroblastoma cell lines, NB1643, NB1, and SH-SY5Y, which harbor R1275 mutated, amplified, and F1174 mutated ALK, respectively." (PMID 27732954, 2016). "The current lack of understanding surrounding the molecular mechanisms of aberrant ALK activity in neuroblastoma is one of the main obstacles to the clinical application of Crizotinib in neuroblastoma patients." (PMID 27732954, 2016). "Our results also identified the transcription factor complex YY1—which promotes neuroblastoma progression by interacting with MYCN —as regulated by ALK." (PMID 27732954, 2016). "It has been reported that neuroblastoma patients bearing both MYCN amplification and ALK mutations are characterized by unfavorable aggressive neuroblastoma phenotype." (PMID 27049722, 2016). "ALK inhibitors have exhibited anti-tumour activity in preclinical models of neuroblastoma, although only modest, responses were observed in a Phase I trial of single agent Crizotinib in paediatric patients." (PMID 27888620, 2016). "Together, our data clearly implicate MYCN as a downstream mediator of ALK signaling in neuroblastoma." (PMID 27732954, 2016). "We examined the effect of PF-06463922 on ALK activity and cell proliferation in neuroblastoma cell lines, in comparison to the well-characterized clinical ALK TKI crizotinib." (PMID 27483357, 2016). "Together, these data demonstrate that ALK promotes neuroblastoma cell progression via the JNK signaling pathway." (PMID 27732954, 2016). "Second, it has been published that cell lines carrying the same mutated ALK (e.g. F1174L in Kelly and LAN-1, both of which are neuroblastoma cell lines) displayed drastically different IC50 to Crizotinib47." (PMID 27641368, 2016). "Neuroblastoma is a pediatric cancer that possesses ALK abnormalities that arise from gene amplification and activating mutations." (PMID 26802023, 2016). "While brigatinib and crizotinib both inhibited cell growth of ALK addicted neuroblastoma lines, they exhibited different IC50 values." (PMID 27049722, 2016). "In neuroblastoma, ALK has been shown to be involved in cell proliferation, migration and invasion and ALK mutations have been reported in around 50% of hereditary and 8-10% of sporadic cases, occurring across all risk groups and more frequently at relapse." (PMID 27888620, 2016). "Doxorubicin, as one of the standard drugs used in neuroblastoma chemotherapy, was selected for evaluating if ALK inhibition influences the combination of chemotherapy with Smac mimetic LCL161." (PMID 27655666, 2016).
neuroblastoma (continued). "Patients with ALK-positive neuroblastoma lack any suitable options for current treatment, despite expression of a bona fide oncogene that has been successfully targeted with crizotinib in other pediatric malignancies." (PMID 27483357, 2016). "Rather than the classic MAPK kinase pathway, our data implicate the ALK-RAS-JNK axis as an important oncogenic signaling pathway in neuroblastoma with activated ALK signaling." (PMID 27732954, 2016). "Here, we describe a deep quantitative phosphoproteomic approach in which Crizotinib-treated neuroblastoma cell lines bearing aberrant ALK are used to investigate downstream regulated phosphoproteins." (PMID 27732954, 2016). "These two serine residues are located in the N-terminal transactivation domain of c-JUN and are known to be specific targets of JNK, further supporting the notion that ALK promotes neuroblastoma progress via JNK signaling." (PMID 27732954, 2016). "We investigated the signaling pathways regulated by ALK in ALK-positive neuroblastoma by comparing the phosphoproteomes of ALK-positive neuroblastoma cell lines following inhibition of ALK by its specific inhibitor Crizotinib." (PMID 27732954, 2016). "Generally, treatment with ALK inhibitors shows an initial strong response in tumors harboring ALK fusion oncogenes, with a less encouraging response observed in ALK-positive neuroblastoma patients." (PMID 27049722, 2016). "Taken together, these preclinical results demonstrate that although crizotinib inhibits growth of the ALK-dependent neuroblastoma cells tested here, efficacy is increased on treatment with PF-06463922." (PMID 27483357, 2016). "This relates either to clinical factors unique to the etiology of this form of neuroblastoma, or alternatively to other issues such as ligand binding or the binding affinity of particular ALK inhibitors for the kinase domain of ALK." (PMID 27483357, 2016). "Finally, the recently reported ligands, FAM150A and FAM150B activate not only the wild type ALK receptor, but also super-activate constitutive active ALK neuroblastoma variants, offering additional options for the inhibition of ALK activity in NB." (PMID 27049722, 2016). "Using RNA interference (RNAi) to knock down ALK in neuroblastoma cells harboring mutant ALK resulted in decreased cell proliferation." (PMID 26771642, 2016). "ALK is amplified in about 14 % of neuroblastomas and while responses occur, particularly in familial cases, resistance in most sporadic cases is high and the value of the ALK inhibitor crizitonib is reduced." (PMID 27821095, 2016). "Our study broadly defines the phosphoproteome in response to ALK inhibition and provides a resource for further clinical investigation of ALK as therapeutic target for the treatment of neuroblastoma." (PMID 27732954, 2016). "In the left panel in which the results from the 4 neuroblastoma cells lines are illustrated, we found the 220 kDa band, which represents the full-length ALK protein, and/or several bands at lower molecular weight (e.g. 140 kDa)." (PMID 27641368, 2016). "Chen and colleagues reported that ALK amplification together with MYCN amplification contributes to the tumorigenesis of neuroblastoma." (PMID 26802023, 2016). "Distinct from the fusion form of ALK found in NSCLC, aberrant ALK in neuroblastoma presents as intact protein with point mutations or amplification." (PMID 27732954, 2016). "Taken together, our data indicate that brigatinib is a potent inhibitor against ALK, supporting further exploration of brigatinib in an ALK-positive neuroblastoma setting." (PMID 27049722, 2016). "Together, these results suggest that PF-06463922 should be further explored as a therapeutic agent in ALK-positive pediatric neuroblastoma." (PMID 27483357, 2016). "Here we investigate the efficacy of a second-generation ALK inhibitor, brigatinib, in a neuroblastoma setting." (PMID 27049722, 2016).
neuroblastoma (continued). "The precise molecular mechanisms of aberrant ALK activity in neuroblastoma remain elusive, limiting the clinical application of ALK as a therapeutic target in neuroblastoma." (PMID 27732954, 2016). "Based on these encouraging clinical responses in NSCLC, we decided to explore the therapeutic potential of brigatinib in the context of ALK-positive neuroblastoma." (PMID 27049722, 2016). "Emerging evidence suggests receptor tyrosine kinase ALK as a promising therapeutic target in neuroblastoma." (PMID 27732954, 2016). "The next-generation ALK inhibitor PF-06463922 is predicted to exhibit increased affinity for ALK mutants prevalent in neuroblastoma." (PMID 27483357, 2016). "Initial experience has shown it is difficult to inhibit growth of ALK-positive neuroblastoma with crizotinib in the clinic even at high dosing levels, motivating investigation of PF-06463922 with its higher affinity for ALK in this setting." (PMID 27483357, 2016). "In contrast to the strong response observed in ALK fusion-positive tumors, patient responses in ALK mutant neuroblastoma are less encouraging." (PMID 27483357, 2016). "The preclinical data presented here clearly show that PF-06463922 is more effective than crizotinib in the inhibition of ALK mutants found in neuroblastoma patients." (PMID 27483357, 2016). "I1171S previously was seen in an in vitro accelerated mutagenesis screen in ALK+ NSCLC using increasing concentrations of crizotinib and somatic mutations in this residue also have been reported in neuroblastoma." (PMID 27009859, 2016). "In summary, we show that brigatinib abrogates ALK activation in neuroblastoma cell lines, in vitro biochemical assays as well as exogenously expressed ALK activity in flies and mice xenografts." (PMID 27049722, 2016). "In a phase 1 clinical trial, a wide range of Crizotinib responsiveness was found in a cohort of ALK+ neuroblastoma patients." (PMID 27641368, 2016). "In agreement, in an ALK/MYCN-driven mouse xenograft neuroblastoma model, brigatinib potently inhibited tumor growth, highlighting tumor inhibition efficacy in vivo." (PMID 27049722, 2016). "Together, these data clearly demonstrate the oncogenic functions of JNK as a downstream mediator of ALK signaling in neuroblastoma." (PMID 27732954, 2016). "We next investigated the function of ALK-regulated phosphorylation of proteins in neuroblastoma by applying several layers of bioinformatic analysis." (PMID 27732954, 2016). "Germline ALK activating mutations are responsible for the majority of hereditary neuroblastoma and somatic ALK activating mutations are also frequently observed in sporadic cases of advanced NB." (PMID 26786851, 2016). "In this study, we adapted a phosphoproteomics platform to study the global effects of the ALK inhibitor Crizotinib in three neuroblastoma cell lines bearing different types of aberrant ALK activity." (PMID 27732954, 2016). "The developmental context in which neuroblastoma arises appears to be particularly important, with many genes associated with aggressive disease (MYCN, ALK) driving cell proliferation and neuritogenesis." (PMID 28035989, 2016). "A carbonitrile derivative, alectinib has potent efficacy against ALK addicted tumors, such as NSCLC expressing EML4-ALK, ALCL expressing NPM-ALK, and ALK amplified neuroblastoma." (PMID 25888090, 2015). "The use of mTOR/AKT inhibitors along with ALK inhibitors have also been recently justified in ALK-altered neuroblastoma." (PMID 26384210, 2015). "Crizotinib was also able to inhibit proliferation and ALK-mediated signaling in a neuroblastoma cell line." (PMID 26678488, 2015). "That phosphorylated ALK was present in many neuroblastoma cell lines is consistent with its role as an important marker, or driver, of neuroblastoma." (PMID 25884760, 2015). "The actionable mutation identified was ALK, which has been identified in 7% of neuroblastoma patients 43 and ALK inhibitors, such as Crizotinib are currently being tested in pediatrics." (PMID 25720842, 2015).
neuroblastoma (continued). "Here we show that FAM150A and FAM150B are potent ligands for human ALK that bind to the extracellular domain of ALK and in addition to activation of wild-type ALK are able to drive 'superactivation' of activated ALK mutants from neuroblastoma." (PMID 26418745, 2015). "Conditioned medium containing either FAM150A or FAM150B was able to activate endogenous ALK signaling in neuroblastoma cells." (PMID 26418745, 2015). "Anaplastic lymphoma kinase (ALK), a receptor tyrosine kinase (RTK), is frequently mutated and activated in both familial and spontaneous neuroblastomas, suggesting that this receptor can prevent a key differentiation step in neural crest cells." (PMID 25884760, 2015). "The anaplastic lymphoma receptor tyrosine kinase, ALK, is mutated in approximately 10% of all spontaneous cases and currently the only therapeutically-targetable receptor tyrosine kinase in neuroblastoma." (PMID 26497213, 2015). "Many different aberrations in the Anaplastic Lymphoma Kinase (ALK) were found to be oncogenic drivers in several cancers including neuroblastoma (NB), therefore ALK is now considered a critical player in NB oncogenesis and a promising therapeutic target." (PMID 26299615, 2015). "R291Q and R335Q corresponded to full-length ALK R1231Q and R1275Q substitutions in neuroblastoma patients." (PMID 25874976, 2015). "Our findings suggest that D5F3 immunohistochemistry, single-color CISH and IT-PGM sequencing are suitable assays for evaluation of ALK status in future neuroblastoma clinical trials." (PMID 25188507, 2014). "Mutations of residues F1174 and I1171 were previously reported in neuroblastoma and crizotinib-resistant ALK+ cell lines and patients." (PMID 24509625, 2014). "Specifically, copy number variations in the central neuroblastoma genes NME1 and ALK, both of which are found to be mutated in neuroblastoma as well support this reasoning." (PMID 25528190, 2014). "Interestingly, ALK expression was recently shown to be associated with less differentiated neuroblastic tumors, as the frequency of ALK positivity in NB was significantly higher than in ganglioneuroblastoma, and in ganglioneuroma." (PMID 24947326, 2014). "The involvement of the ALK gene in neuroblastoma and neurological disorders is indeed consistent with its preferential expression in the central and peripheral nervous systems that has been reported in mammals." (PMID 24811761, 2014). "This suggests an approach that can be adapted to provide crucial clinically relevant information for the stratification of neuroblastoma patients onto therapy with an ALK inhibitor." (PMID 25133137, 2014). "Recent reports have suggested that both mutant ALK and Lin28B promote the growth of neuroblastomas in transgenic mouse models by targeting MYCN for stabilization or overexpression." (PMID 24391509, 2014). "High-level ALK genomic amplification, although infrequent (prevalence 5% or less), has also been reported as an adverse prognostic factor in neuroblastomas in some studies." (PMID 25188507, 2014). "In conclusion, we have evaluated several platforms for the ascertainment of ALK status in neuroblastomas." (PMID 25188507, 2014). "Recently introduced targeted therapies for neuroblastoma patients include the small molecule inhibitor Crizotinib, which targets the receptor tyrosine kinase Anaplastic Lymphoma Kinase (ALK) and was well tolerated in a recent Phase 1 dose-escalation trial." (PMID 25133137, 2014). "ALK protein expression in neuroblastomas has been reported as an adverse prognostic factor by several groups." (PMID 25188507, 2014). "For example, neuroblastoma presented with only one ML-skewed gene family (the ALK/LTK receptor tyrosine kinases), which includes driver mutations known to activate ALK in this disease." (PMID 24806839, 2014). "The anaplastic lymphoma kinase (ALK) gene is overexpressed, mutated or amplified in most neuroblastoma (NB), a pediatric neural crest-derived embryonal tumor." (PMID 24947326, 2014).